MTOR (mechanistic target of rapamycin kinase)
Diseases named in the same sentence as MTOR in open-access papers (continued):
Sharing a sentence is not in itself a finding about the gene and the disease.
cancer (continued). "In addition, second generation, ATP-competitive inhibitors of mTOR need to be combined with miRNAs and tested to evaluate the potential of using this approach as a chemotherapeutic tool in cancer." (PMID 23434669, 2013). "Erk and Akt are two other mediators of mTOR in cancer cells." (PMID 23667692, 2013). "Similarly, the constitutively activated class I PI3K/Akt pathway inhibits both apoptosis and autophagy because it acts as a positive regulator of the mTOR signaling pathway and plays a crucial role in cancer cell survival." (PMID 24053190, 2013). "In an effort to circumvent resistance to rapamycin – an mTOR inhibitor - we searched for novel rapamycin-downstream-targets that may be key players in the response of cancer cells to therapy." (PMID 24204783, 2013). "And the mutations in the mTOR gene have been identified in a few human cancers; however, the mechanism has not been well established to date." (PMID 23940798, 2013). "Based on recent reports that c-Src is involved in translation initiation through AKT/mTOR signaling in human cancer cells, we hypothesized that c-Src is a major mediator for α6β4 dependent mTOR activation." (PMID 24180592, 2013). "BEZ235 is a PI3K/mTOR inhibitor which induces cell cycle arrest and apoptosis in cancers." (PMID 24349524, 2013). "In addition to the recently launched mTOR inhibitor everolimus, which is used for the treatment of a broad range of cancer types, a number of small molecule inhibitors of the PI3K/mTOR signaling pathway are currently in clinical development." (PMID 23826249, 2013). "Many human cancers exhibit an enhanced activation of mTOR, resulting in reduced autophagy." (PMID 23451179, 2013). "Furthermore, the simultaneous inhibition of glycolysis and the mTOR pathway is a potentially less toxic approach to target cancer cells." (PMID 24024216, 2013). "Another strategy for targeting the mTOR pathway as a therapeutic tool in cancer is miRNAs." (PMID 23434669, 2013). "Consequently, mTOR has emerged as a key target for the treatment of cancer and a number of mTOR inhibitors are being examined by clinical trials." (PMID 23594524, 2013). "We observed that resveratrol down-regulated PKM2 expression by inhibiting mTOR signaling and suppressed cancer metabolism, adjudged by decreased glucose uptake, lactate production (aerobic glycolysis) and reduced anabolism (macromolecule synthesis) in various cancer cell lines." (PMID 22574221, 2012). "There are numerous reports further beyond the scope of this review regarding the role of AKT/mTOR in survival pathways, and how targeted disruption of metabolic pathways may be used to sensitize cancer cells to apoptosis." (PMID 22680924, 2012). "mTOR is now considered a substantiated target in the treatment of cancer." (PMID 22408430, 2012). "Stratification of patients and selection of drug combination therapies may enhance the efficacy of mTOR inhibition, leading to a more effective and personalized cancer therapy." (PMID 22408430, 2012). "In addition, enhanced signaling through Ras, Akt, and mTOR also contributes to the survival and growth of cancer cells during hypoxia." (PMID 22523603, 2012). "The critical connection of mTOR to the PI3K/AKT pathway has led to the prediction that the targeting of mTOR may be useful in cancer therapy." (PMID 22666248, 2012). "PI3K signals to Akt, which activates the mTor complex, leading to migration of cancer cells." (PMID 23055980, 2012). "In addition, the identification of mTOR gene as a notable target of mir-99a and mir-99b opens the door to the possibility of therapeutic applications for mir-99a and mir-99b in cancer-like diseases such as Lymphangiomyelomatosis." (PMID 22299047, 2012).
cancer (continued). "In addition, at least partly, the suppression of PI3K/Akt by HRT induces dephosphorylation of mTOR and GSK3β, resulting in the inhibition of cancer cell proliferation." (PMID 22899960, 2012). "In certain cancers, resistance to antineoplastic agents such as topoisomerase 1, topoisomerase 2 inhibitors and methotrexate can be overcome with a synergistic combination with mTOR inhibitors." (PMID 22214493, 2012). "Indeed, there now exist multiple pharmacological inhibitors of the PI3K/Akt/mTOR pathway which have entered clinical trials for adult and pediatric cancer." (PMID 23056595, 2012). "Thus, in cancer cells metformin inhibited insulin-stimulated mTOR activation and proliferation in an AMPK-dependent manner." (PMID 22421948, 2012). "The dysregulation of mTOR pathway can be observed in human diseases, especially certain cancers, and there are also some mTOR inhibitors, which are beginning to be used in the treatment of cancer." (PMID 23226337, 2012). "This review will first evaluate potential uses of Raf, MEK, PI3K, Akt and mTOR inhibitors that have been investigated in pre-clinical and clinical investigations and then discuss how cancers can become insensitive to various inhibitors and potential strategies to overcome this resistance." (PMID 23085539, 2012). "In addition to preclinical studies, clinical observations support the targeting of the PI3K/Akt/mTOR pathway in human cancer." (PMID 22545054, 2012). "The signaling pathways that regulate mTOR activity are frequently activated in human cancers." (PMID 23342262, 2012). "Therefore, inhibitors of the PI3K/Akt/mTOR pathway have emerged as important and attractive therapeutic strategies for cancer therapy." (PMID 22246348, 2012). "Indeed, rapamycin and its derivatives inhibit mTOR activation, induce autophagic cell death and are under clinical investigation as anti-cancer compounds." (PMID 24710492, 2012). "Deregulation of multiple elements of the mTOR pathway has been reported in many types of cancers." (PMID 22408430, 2012). "Together, a number of recent studies have provided the molecular basis for the observation that small-molecule inhibitors of PI3K/Akt/mTOR signaling represent a potent strategy to enhance the sensitivity of cancer cells toward cell death induction via the mitochondrial pathway of apoptosis." (PMID 23061040, 2012). "Characterisation of both the planarian mTORC1 signalling components and another PIKK family member as key regulators of regeneration and growth will influence future work on regeneration, growth control, and the development of anti-cancer therapies that target mTOR signalling." (PMID 22479207, 2012). "PIK3CA mutations are frequently diagnosed in diverse cancers and may predict response to PI3K/AKT/mTOR inhibitors." (PMID 23248156, 2012). "MTOR signaling pathway is a key signal-transduction system that links multiple receptors and oncogenic molecules to diverse cellular functions and is inappropriately activated in many human cancers." (PMID 23173671, 2012). "PI3K/Akt/mTOR signaling dysregulation play a key role in the onset of human cancers." (PMID 22885370, 2012). "mTOR inhibitors are currently under development for potential anti-cancer drugs." (PMID 22403675, 2012). "In addition, combinational therapy aimed at Shh and mTOR signaling inhibition, together with standard chemotherapy, proved to be capable of selectively eliminating cancer stem cells." (PMID 22264265, 2012). "Understanding of mTOR signaling provided the biological basis for targeted chemotherapeutics development, including several rapamycin analogues for treating breast and other cancers." (PMID 23369283, 2012). "A number of mechanisms can lead to primary or acquired resistance of cancer cells to mTOR inhibitors, including activation of alternative pathways, due to other mutations, and excessive reactivation of AKT feedback resulting in overactivation of the insulin-growth factor." (PMID 23344019, 2012).
cancer (continued). "Eventually, the study of the mTOR pathway may bring novel insights into mTOR biology, and also assist in the development of more effective therapeutic strategies for treating mTOR-related diseases, particularly cancer." (PMID 22408430, 2012). "In cancer, mTOR is frequently hyperactivated which promotes cancer development and progression." (PMID 22214493, 2012). "S6K1 is another mTOR target that plays a role in the apoptosis resistance of cancer cells." (PMID 22246168, 2012). "mTOR/S6K pathway plays an important role in normal and cancer cell." (PMID 22570651, 2012). "Thus, mTOR signalling is activated in conditions of proliferation deregulation and in many cancer types." (PMID 22408430, 2012). "Activation of the PI3K/Akt/mTOR signaling network is a common feature of most human cancers." (PMID 22888331, 2012). "Serine-threonine kinase mTOR has emerged as a key negative regulator of autophagy in cancer cells." (PMID 22457718, 2012). "In addition, AKT activation (which is increased in many cancers) leads to increased mTOR activation and blockage of autophagy." (PMID 24710492, 2012). "Mutations in mTOR gene that confer constitutive activation of mTOR signalling, even under nutrient starvation conditions, have been identified in a few human cancers, although not clearly linked to tumour development." (PMID 22408430, 2012). "Since AKT and Rac1 require each other for their activation, our findings suggest that loss of miR-204 expression in human tumors may induce the positive feedback loop between BDNF/AKT1/mTOR and Rac1 during cancer cell migration and invasion." (PMID 23285024, 2012). "Deregulation of multiple elements of the mTOR pathway (PI3K amplification/mutation, PTEN loss of function, AKT overexpression, and S6K1, 4EBP1 and eIF4E overexpression) has been reported in cancer, such as breast, ovarian, renal, colon and head and neck cancers." (PMID 22408430, 2012). "Activation of PI3K/AKT/mTOR pathway has been illustrated as an early event in multiple human cancers, suggesting that targeting the PI3K/AKT/mTOR pathway may have chemopreventive value." (PMID 22666248, 2012). "In addition, the newly developed inhibitors ZSTK474 and KP372-1 which selectively target pan-class I PI3K and Akt, respectively, and Rapamycin which has been well-established as highly specific mTOR inhibitor, decrease viability of canine cancer cell lines." (PMID 22647622, 2012). "mTOR was found to be an upstream activator of HIF-1α expression in cancer cells." (PMID 22992293, 2012). "The combination of mTOR inhibitors with angiogenesis inhibitors could be a useful tool for cancer therapy." (PMID 22570651, 2012). "In conclusion, most OSCC tumours showed mTOR activation, suggesting that mTOR could be a promising target for anti-cancer therapy against OSCC." (PMID 22333597, 2012). "The effects of dual inhibition of IGF-1R and mTOR have been examined in myeloma and other cancers." (PMID 23085539, 2012). "Moreover, the in vitro activity of these ATP-competitive PI3K/mTOR modulators has translated well in in vivo models of human cancer xenografted in mice." (PMID 23085539, 2012). "Although it should be pointed out that there are some clinical trials in progress to determine whether it is beneficial to treat cancer patients with a PI3K/mTOR dual inhibitor and an mTORC1 blocker such as NVP-BEZ235 and RAD001." (PMID 23085539, 2012). "mTOR functions as a central controller of growth, proliferation, metabolism and angiogenesis, but its signaling is dysregulated in various human diseases especially certain cancers like renal cell carcinoma and breast cancer." (PMID 22214493, 2012). "In the current study, we show that the synergistic combination of RAD001 and BEZ235 is not restricted to these two tumor types, but rather inhibits mTOR signaling, cell viability and tumorigenesis broadly in several different cancer lines, representing various lineages and genetic backgrounds." (PMID 23155392, 2012).
cancer (continued). "Based on the recent study a small reduction in PTEN gene expression can trigger cancer susceptibility, the higher level of PTEN in SNU-668 would play an enhanced role as a negative regulator of STAT3 and mTOR, consequently resulting in more significant molecular change of signaling." (PMID 22159814, 2012). "Similarly, inhibitors of the mammalian target of rapamycin (mTOR), which reduces phosphorylation of 4E-BPs, exert anti-cancer activity in vitro and in vivo." (PMID 22935625, 2012). "Refractory cancers that develop activation of PI3K/mTOR signaling in the process of tumor de-differentiation may be particularly attractive targets for therapy." (PMID 23077520, 2012). "Moreover Akt is known to play a crucial role in PI3k/Akt/mTOR pathway which is important in other types of cancers where numbers of inhibitors are examined in this direction." (PMID 23091605, 2012). "Mutation, deletion, or epigenetic silencing of PTEN has been shown to correlate with poor prognosis and reduced survival in patients with various types of cancer, with loss of PTEN being a common mechanism for activation of the PI3K/Akt/mTOR pathway and poor prognosis." (PMID 22545054, 2012). "Identification of the Akt and mTOR substrates that control various aspects of B cell function could lead to novel targets for therapeutic intervention in immune diseases and cancer." (PMID 22888331, 2012). "Honokiol-mediated inhibition of mTOR also suggests that honokiol and its derivatives may prove excellent candidates as targeted therapies for carcinomas characterized by hyperactive mTOR signaling." (PMID 22353783, 2012). "Furthermore increased expression of the Ras/PI3K/Akt/mTOR pathway also occurs frequently in some cancers as the PIKC3A gene is amplified in approximately 40% of ovarian cancers." (PMID 21422497, 2011). "However, resistance of some cancers to mTOR-directed therapeutics has limited the success of mTOR inhibitors." (PMID 21320304, 2011). "Previous studies have indicated that many cancers are mTOR dependent." (PMID 21487160, 2011). "Sirolimus inhibits mTOR and may be a potential therapeutic alternative for cancers for which the mTOR-Akt pathway is activated." (PMID 21437186, 2011). "Given that cancer (like aging) is “a form of growth”, the mTOR pathway is activated in cancer." (PMID 22166724, 2011). "Consequently, inhibitors of mTOR, have been developed and assessed for their safety and efficacy in patients with cancer." (PMID 21906310, 2011). "Therefore, the inhibition of the mTOR pathway has been considered as an appropriate approach for cancer therapy." (PMID 22145042, 2011). "These trials have shown that mTOR inhibitors are well tolerated and may induce prolonged stable disease and tumor regressions in cancer patients." (PMID 22091432, 2011). "Thus, cancers driven by hyperactive mTOR signaling would be hypersensitive to treatment with rapamycin, and this is often the case in cell culture and mouse models." (PMID 21378410, 2011). "Could a similar story be on the horizon for mTOR inhibitors for which the principal indication has also been in the treatment of cancers?" (PMID 22132311, 2011). "Dysregulation of the PI3K/Akt/mTOR signaling pathway is common in human cancers." (PMID 24212820, 2011). "But even cancer-promoting damage is not random: mutations activate growth-promoting pathways including PI3K/mTOR, the most universal alteration in cancer." (PMID 22166724, 2011). "Indeed, AZD8055, a specific mTOR inhibitor, showed antiproliferative effects in various cancer models that were superior to those of rapamycin." (PMID 24212820, 2011).
cancer (continued). "Interestingly, we found that CNI-induced VEGF overexpression and cancer cell proliferation was inhibited by rapamycin treatment, indicating potential involvement of the mammalian target of rapamycin (mTOR) pathway in this tumorigenic process." (PMID 21886838, 2011). "Furthermore, a function for mTOR in cancer invasion and metastasis has also been demonstrated and mTOR plays an emerging role in cell metabolism." (PMID 24212820, 2011). "MTOR is strongly involved in growth, survival, metabolism, and cancer development." (PMID 21904669, 2011). "Mutations at other genes (e.g., in components of the Ras/PI3K/PTEN/Akt/mTOR pathway) have been hypothesized to be also necessary for malignant transformation in some cancers." (PMID 21422497, 2011). "Of note, ATP-competitive inhibitors of mTOR have also shown efficacy in tumor models of genetically engineered mice, which may reflect the pathogenesis of human cancers more closely than xenograft models." (PMID 24212820, 2011). "Next, we wished to examine whether eIF4E activities within tumour cells predict clinical responses to mTOR inhibition in cancer patients, and whether changes in eIF4E activities after treatment reflect these responses." (PMID 21320304, 2011). "For instance, inhibitors of mTOR (some of which are already approved for cancer treatment) decrease the level of HIF-1α, and it has been suggested that their efficacy might be assessed by their ability to reverse tumour-associated 18FDG uptake." (PMID 21612605, 2011). "In addition, PA can bind and activate the mammalian target of rapamycin (mTOR), a protein kinase well known for its roles in cell survival and cancer." (PMID 22136116, 2011). "Finally, emerging data show that the role of mTOR in cancer biology is not limited to the proliferating cancer cells but involves the tumor microenvironment." (PMID 24212820, 2011). "However, recent findings have revealed the complexity of the functions of mTOR in cancer and have helped develop new strategies to improve the anticancer efficacy of mTOR inhibitors." (PMID 24212820, 2011). "Finally, activation of Mek/Erk signaling pathway following exposure of cancer cells to ATP-competitive inhibitors of mTOR has also been reported even with dual PI3K/mTOR inhibitors." (PMID 24212820, 2011). "There are 3 links between aging and cancer that are in part mTOR-dependent." (PMID 22267462, 2011). "The serine-threonine kinase mammalian target of rapamycin (mTOR) is deeply involved in the regulation of protein translation, cell growth, and metabolism and is deregulated in several pathologies, such as aging, metabolic diseases and cancer." (PMID 21391908, 2011). "Given that mTOR activation isregulated mainly by the IGF-1/AKT pathway, attenuation of AKT activity as observed in ourexperimental cancer cachexia model should further facilitate protein translation inhibitiondue to mTOR inactivation and the consequent hypophosphorylation of EIF4Ebp1." (PMID 21069263, 2011). "Separating FKBP51 inhibition from mTOR inhibition in anticancer therapy may sometimes be useful, according to recent studies that propose a role for autophagy in promoting cancer survival and enhancing the threshold for apoptosis." (PMID 22087835, 2011). "Among the human disorders that involve dysregulation of mTOR signaling is cancer." (PMID 22242130, 2011). "Inhibition of Raf, MEK, PI3K, Akt and mTOR may prove useful in cancer treatment as well as in preventing or suppressing cellular aging." (PMID 21422497, 2011). "Therefore, the PI3K/Akt/mTOR network is considered as a validated target for innovative cancer therapy." (PMID 20671809, 2010). "Interestingly, in some cancer histologies up-regulation of pAKT following mTOR inhibition has been seen both in preclinical models and in patients on receiving rapalogs in clinical trials." (PMID 20543980, 2010).